HSD17B2 (hydroxysteroid 17-beta dehydrogenase 2)
Description:
Catalyzes the NAD-dependent oxidation of the highly active 17beta-hydroxysteroids, such as estradiol (E2), testosterone (T), and dihydrotestosterone (DHT), to their less active forms and thus regulates the biological potency of these steroids. Oxidizes estradiol to estrone, testosterone to androstenedione, and dihydrotestosterone to 5alpha-androstan-3,17-dione. Also has 20-alpha-HSD activity.
Synonyms: EDH17B2; SDR9C2; HSD17
Tractability: Small molecule: a high-quality ligand is known; it belongs to a druggable protein family. Antibody: UniProt predicts a signal peptide or a membrane-spanning region. PROTAC: its protein half-life has been measured; a small molecule that binds it is known.
Target class: Enzyme; Oxidoreductase
Chemical probes: CHEMBL2324690
Gene: Protein-coding gene on chromosome 16 (82,034,988 to 82,098,534, forward strand). Ensembl gene ENSG00000086696.
Subcellular location: Endoplasmic reticulum membrane
Subcellular location (Human Protein Atlas): Endoplasmic reticulum
Pathways (Reactome):
Metabolism: Estrogen biosynthesis
Gene Ontology:
Molecular function: estradiol 17-beta-dehydrogenase [NAD(P)+] activity; protein binding; testosterone dehydrogenase (NAD+) activity; 17-alpha,20-alpha-dihydroxypregn-4-en-3-one dehydrogenase [NAD(P)+] activity; 17-beta-hydroxysteroid dehydrogenase (NAD+) activity; oxidoreductase activity, acting on the CH-OH group of donors, NAD or NADP as acceptor
Biological process: androgen metabolic process; estrogen biosynthetic process; response to retinoic acid; androgen biosynthetic process
Cellular component: endoplasmic reticulum membrane
Genetic constraint (gnomAD): Loss-of-function variants: 34 observed, 28.86 expected, observed/expected ratio (o/e) 1.18, 90% interval 0.89 to 1.57. The synonymous counts are far from expectation, so gnomAD's model fits this gene poorly and the ratio says little. Missense variants: 613 observed, 490.32 expected, observed/expected ratio (o/e) 1.25, 90% interval 1.17 to 1.34. Synonymous variants: 246 observed, 196.65 expected, observed/expected ratio (o/e) 1.25, 90% interval 1.13 to 1.39.
Homologues: Orthologues: chimpanzee HSD17B2 (99% identical), macaque HSD17B2 (92% identical), pig HSD17B2 (67% identical), dog HSD17B2 (66% identical), rabbit HSD17B2 (66% identical), guinea pig HSD17B2 (61% identical), rat Hsd17b2 (61% identical), mouse Hsd17b2 (59% identical), tropical clawed frog hsd17b2 (44% identical), zebrafish hsd17b2 (34% identical). Paralogues in human: HSD11B2 (37% identical), RDH16 (28% identical), BDH1 (26% identical), HSD17B6 (26% identical), SDR9C7 (26% identical), RDH5 (25% identical), DHRS9 (25% identical), HSD17B4 (19% identical), SDR16C5 (18% identical), HSD17B14 (18% identical), RDH10 (18% identical), RDH11 (17% identical), and 13 more.
Diseases named in the same sentence as HSD17B2 in open-access papers:
HSD17B2 is named in the same sentence as 34 diseases in open-access papers, as found by Europe PMC text mining. Sharing a sentence is not in itself a finding about the gene and the disease. The quoted sentences say what the papers report.
prostate carcinoma (9 papers, 2017 to 2024). A carcinoma that arises from epithelial cells of the prostate gland. "In prostate cancer, HSD17B2 SNPs rs4243229 and rs7201637 were associated with progression in both Caucasian and Taiwanese cohorts studied." (PMID 28430630, 2017). "Regarding other ER+ cancer types, HSD17B2 expression and its different polymorphisms showed an inverse relationship with PFS and OS in prostate cancer in patients with ERα-positive tumours." (PMID 36674737, 2023). "HSD17B2 expression is reduced in prostate cancer patients, and consistently a HSD17B2 gene deletion was found in both primary and metastatic prostate cancer." (PMID 35582223, 2020). "The healthy prostate expresses HSD17B2 and the amount of HSD17B2 expression is reduced in prostatic carcinoma compared to benign hyperplasia." (PMID 28430630, 2017). "Likewise, the AI treatment group significantly inhibited expression of hsd17b2 mRNA in ricefield eels, and it has been reported that overexpression of hsd17b2 in prostate cancer cell lines diminished androgen receptor signaling and suppressed androgen-induced cell proliferation." (PMID 39201749, 2024). "Genes involved in steroid synthesis included CYP21A2, HSD17B2, ITGA6, IDI2, MAP2K1, PMVK, TSPO, and may correspond to androgen dependent growth of prostate cancer." (PMID 32226005, 2020).
breast carcinoma (7 papers, 2011 to 2025). "In breast cancer cell line T-47D, which is ERα- and AR-positive, treatment with the aromatase inhibitor exemestane was shown to result in increased HSD17B2 expression, a change which was associated with increased DHT expression." (PMID 28430630, 2017). "For example, high intratumoural expression of HSD17B enzymes involved in E1 synthesis, such as HSD17B2, HSD17B10 and HSD17B14, are associated with lower OS and/or DMFS in ER+ breast cancer patients." (PMID 36674737, 2023). "These HSD17B1 and HSD17B2 isoforms were amplified at ~1.4% and ~0.6% in breast cancer, respectively." (PMID 31060224, 2019). "HSD17B1 has been shown to be under the regulation of microRNAs 210 and 518c in placental cells and microRNAs-10b, 145, 342, 17, 26a and 106b have been predicted to interact with HSD17B1 and HSD17B2 in breast cancer." (PMID 28430630, 2017). "The miRNAs control of the expression of HSD17B1 or HSD17B2 in breast cancer cells was examined using 50 miRNAs selected as described in the methods section." (PMID 28977936, 2017). "We aimed to investigate if estrogen and androgen-mediated signaling can influence the expression of HSD17B1 and HSD17B2 in breast cancer cell lines." (PMID 28977936, 2017). "To date, no study has been published examining the role of miRNAs regarding HSD17B1 and HSD17B2 in breast cancer." (PMID 28977936, 2017). "Here we demonstrate that estradiol alters the expression of HSD17B1 and HSD17B2, two of the enzymes responsible for mediating the activity of estradiol in breast cancer cell lines." (PMID 28977936, 2017). "The expression of HSD17B2 in breast cancer is important in its capacity to oxidize E2 into E1 and protect the tissue from its activity, and HSD17B2 expression was shown to be reduced in breast cancer compared with benign tumors." (PMID 28430630, 2017). "In conclusion, we show that estradiol negatively regulates HSD17B1 in breast cancer cell lines, and a possible time sensitive modulator of HSD17B2." (PMID 28977936, 2017). "Taken together, these findings are the first to characterize miRNAs controlling HSD17B1 and HSD17B2 in breast cancer cell lines." (PMID 28977936, 2017). "While this review focused on the roles of HSD17B1 and HSD17B2, in breast cancer, this section will briefly describe other family members of note, with a focus on their role in breast cancer." (PMID 28430630, 2017). "Furthermore, HSD17B2 mRNA expression has been shown to be inversely correlated to E2 levels in breast cancer and to the majority of adverse clinical factors studied." (PMID 28430630, 2017). "We show that HSD17B1 and HSD17B2 are controlled by estradiol, dihydrotestosterone, and miRNAs, as well as modulated by several breast cancer-related genes, which could have future clinical applications." (PMID 28977936, 2017). "Not much is known about the control of the expression of HSD17B1 and HSD17B2 in breast cancer, apart from that they are correlated with ERα expression, and that dihydrotestosterone can induce HSD17B2 expression in an AR-dependent manner in the breast cancer cell line T-47D." (PMID 28977936, 2017). "Collectively, these findings indicate that ERα-dependent estradiol signaling in breast cancer cell lines results in a reduction in HSD17B1, with a possible time-dependent effect on HSD17B2." (PMID 28977936, 2017). "Lastly, we show that the poorly characterized miR-579-3p is a potent down regulator of HSD17B2 in ZR-75-1 and MCF10A, providing some of the first hints as to its role in breast cancer." (PMID 28977936, 2017). "We found eight miRNAs which modulate HSD17B1 or HSD17B2 expression, and five genes which appear able to control HSD17B1 or HSD17B2 expression in breast cancer cell lines." (PMID 28977936, 2017). "Besides their role in breast cancer, which is relatively well-documented, HSD17B1 and HSD17B2 are also involved in several other forms of cancer." (PMID 28430630, 2017).
breast carcinoma (continued). "The role of HSD17B2 in ERα-negative breast cancer is likely different since its expression has been shown to be increased." (PMID 28430630, 2017). "Furthermore, we aimed to identify microRNAs responsible for the regulation of HSD17B1 and HSD17B2 and to identify genes which control the expression of HSD17B1 and HSD17B2 in breast cancer cell lines." (PMID 28977936, 2017).
colorectal cancer (4 papers, 2011 to 2022). A primary or metastatic malignant neoplasm that affects the colon or rectum. "In that study the authors report three SNPs, rs10046 in CYP19A1, rs2911422 and rs2042429 in HSD17B2 genes, that were marginally associated with colorectal cancer risk." (PMID 36302831, 2022). "We observed little support for an association of gene variants in hormone receptors (ESR1, ESR2, PGR) and active estrogen synthesizers (HSD17B1, HSD17B2, and HSD17B4) with colorectal cancer risk among postmenopausal women of European descent." (PMID 21627810, 2011). "FABP6, hypermethylated SFRP1, XDH, PLAU, ADH1C, HSD17B2, and SPP1 have been identified more as a colorectal cancer biomarker than as a therapeutic target at present." (PMID 34381520, 2021).
colon cancer (2 papers, 2017 to 2022). "The expression of HSD17B2, which catalyzes estradiol (E2) to E1 in human CRC tissue, was also proven to be downregulated in colon cancers and predicts poor prognosis, suggesting an important role of estrogen metabolism in CRC progression." (PMID 35664769, 2022).
endometriosis (2 papers, 2023). The growth of functional endometrial tissue in anatomic sites outside the uterine body. "However, in pathological condition such as endometriosis, progesterone is unable to induce the expression of HSD17B2 in epithelial cells owing to the defect of stromal cells." (PMID 37583433, 2023). "Then, the inability of endometriosis epithelial cells to express HSD17B2 may decrease the PR-B level in stromal cells, contributing to excessive estradiol production." (PMID 37447296, 2023).
COVID-19 (1 paper, 2022). A disease caused by infection with severe acute respiratory syndrome coronavirus 2. "Using network pharmacology, we identified 7 core targets of curcumol against COVID-19 and COAD, including GABRD, GABRP, BCHE, CYP3A4, PGR, HSD17B2, and SLC6A3." (PMID 35967794, 2022).
diabetes (1 paper, 2022). "Our proteomic analysis and PRM validation confirmed that HSD17B2 and HSD17B6 were both significantly downregulated in db/db mice compared with bks mice, which could provide insights into the association between HSD17B2 or HSD17B6 and NAFLD and diabetes based on steroid metabolism." (PMID 36077090, 2022).
gastric cancer (1 paper, 2012). A primary or metastatic malignant neoplasm involving the stomach. "The objective of the study was to investigate the role of genes (HSD3B1, CYP17A1, CYP19A1, HSD17B2, HSD17B1) involved in the steroid hormone biosynthesis pathway and progesterone receptor (PGR) in the etiology of gastric cancer in a population-based two-phase genetic association study." (PMID 23110082, 2012).
hyperadrenocorticism (1 paper, 2018). "It would be reasonable to expect increased HSD17B2 mRNA expression in ST for the same reason it was increased in the hyperadrenocorticism cohort, i.e., homeostasis response to elevated adrenal sex steroids." (PMID 30356827, 2018). "Given that HSD17B2 is responsible for the intracellular inactivation of sex steroids, particularly testosterone in the liver, it is intriguing to speculate that it plays a role in the pathogenesis of atypical hyperadrenocorticism in ST." (PMID 30356827, 2018). "HSD17B2 was over-expressed in the dogs with hyperadrenocorticism in comparison to both the normal and ST dogs; and, while not significant, it was slightly under-expressed in ST in comparison to normal dogs." (PMID 30356827, 2018).
Miscarriage (1 paper, 2023). A pregnancy that ends at a stage in which the fetus is incapable of surviving on its own, defined as the spontaneous loss of a fetus before the 22th week of pregnancy. "Interestingly, the expression levels of TPPP3 and HSD17B2 also decreased in the decidual tissues of patients with miscarriage." (PMID 37583433, 2023).
non-small cell lung carcinoma (1 paper, 2024). A group of at least three distinct histological types of lung cancer, including non-small cell squamous cell carcinoma, adenocarcinoma, and large cell carcinoma. "Decreased expression of HSD17B2, an enzyme catalyzing steroid hormones and maintaining hormone balance, appears to be a frequent feature in non-small cell lung cancer." (PMID 39337373, 2024).
ovarian carcinoma (1 paper, 2012). A malignant neoplasm originating from the surface ovarian epithelium. "We see that E2F1 expression is elevated in ovarian cancer, while HSD17B2 expression is reduced." (PMID 22548828, 2012). "Thus, we predict that E2F1 negatively regulates HSD17B2 in ovarian cancer and that reduced HSD17B2 results in an excess of estradiol, which in turn activates cell-proliferation genes through the activation of ESR1." (PMID 22548828, 2012).
ovarian tumours (1 paper, 2023). "In addition, increased expression of the E1 synthetic enzymes HSD17B2, HSD17B4 and HSD17B6 in ovarian tumours is inversely associated with the probability of PPS (HR = 1.21 (1–1.45), p = 0.045; HR = 1.29 (1.07–1.55), p = 0.0073; respectively)." (PMID 36674737, 2023). "Moreover, elevated intratumoural E1 synthesis by HSD17B2, HSD17B4, HSD17B6 and HSD17B14 overexpression in primary ovarian tumours correlate with lower OS." (PMID 36674737, 2023).
SARS-CoV infection (1 paper, 2020). "Another study showed that the coding gene for hydroxysteroid 17-beta dehydrogenase 2 (HSD17B2) was downregulated in SARS-CoV infection, which is a consequence of stimulation of IL-1, IL-6, and TNFα as well as induction of inflammation." (PMID 32754004, 2020).
schizophrenia (1 paper, 2024). A major psychotic disorder characterized by abnormalities in the perception or expression of reality. "Of the 19 molar ratios that may reflect a balance between AKR1C1 and HSD17B2, 3 are lower, 11 are not significantly different, and 5 are higher in patients compared with controls (p = 0.494, Mann–Whitney test), suggesting the absence of a significant trend in relation to schizophrenia." (PMID 39201417, 2024).
skin aging (1 paper, 2023). The gradual irreversible changes in structure of skin that occur as a result of the passage of time.. "Then, we confirmed the down-regulated expressions of ABCC4, PTGER3, BCEH, HPGD, and MOXD1 in normal group, while AR, CXCR2, HSD17B2, ODC1, PI3, PLAU and THBS2 were up-regulated in skin aging group." (PMID 37310405, 2023).
uterine corpus endometrial carcinoma (1 paper, 2023). A endometrial carcinoma (disease) that involves the body of uterus. "In this sense, we found hypomethylation of the HSD17B2 promoter and overexpression of this enzyme in uterine corpus endometrial carcinoma (UCEC) compared to normal tissue." (PMID 36674737, 2023).
uterine tumour (1 paper, 2023). "In this sense, we found hypomethylation of the enzyme HSD17B2 in cancer samples, which, as expected, also showed a higher level of expression in samples of uterine tumour tissue." (PMID 36674737, 2023).
tumor (12 papers, 2009 to 2025). "Only increased expression of cystatin CST6 (implicated in tumor suppression) and of the dehydrogenase HSD17B2 (involved in sterol metabolism) were common to both PHKs and HaCaT." (PMID 23702334, 2013). "Intratumoural enzymes that inactivate potent androgens (e.g., HSD17B2) exhibited similar tumour aggressiveness-linked downregulation, as reported in advanced forms of classical steroid-dependent cancers, whereas there was little change in the corresponding activating enzymes." (PMID 39342807, 2024). "Consistent with this, reanalysis of the TCGA PRAD cohort (n = 497) showed that tumor T-stage progression was associated with SRD5A1 and HSD17B3 gene amplification and gain, but shallow or deep deletion of SHBG and HSD17B2 genes." (PMID 34298692, 2021). "Down-regulation was seen for CNTN1, CXCL13, MAOB, PAGE4, PENK, SPOCK3 in CP compared to NP as well as for HSD17B2, SALL1, TRPA1 for tumor-associated bladder stromal cells compared to normal bladder." (PMID 19737398, 2009). "Additionally, dynamic IPA site usage was observed in well-known tumor suppressor genes, including TSC1, HSD17B2, CD58, RUNX1 and INPP4B." (PMID 41218079, 2025).
cancer (9 papers, 2016 to 2024). A tumor composed of atypical neoplastic, often pleomorphic cells that invade other tissues. "MiR-498 is frequently downregulated in several forms of cancer, and we show downregulation of HSD17B2 upon treatment with miR-498, suggesting a pro-estrogenic role of this miRNA." (PMID 28977936, 2017). "Protein levels of HSD17B2 were in general significantly increased (p = 0.0236) in cancer as compared to adjacent control tissue with unchanged levels in 5 pairs, decreased levels in 11 pairs, and increased levels in 24 out of 40 pairs." (PMID 28690541, 2017). "Additionally, both HSD17B1 and HSD17B2 gene isoforms were found to be amplified minimally (0–1.4%) in different hormone sensitive cancers studied." (PMID 31060224, 2019). "Our current Western blotting showed increased protein levels of HSD17B2 in cancer endometrium in 7 out of 17 paired samples while IHC revealed significantly increased protein levels in EC samples compared to adjacent control tissue but with lower levels seen in 11 EC samples out of 40 investigated." (PMID 28690541, 2017). "In contrast, Caco2 cells, also ERβ-negative but with high HSD17B2 expression, did not respond to E2 stimulation, suggesting that HSD17B2 influences the local availability of E2, thus affecting the cancer cells’ ability to respond to E2-induced proliferation." (PMID 39030619, 2024).
HSD17B2 also shares sentences with these, for which no sentence is quoted: endometrial cancer (2 papers); liver cancer (2); adenovirus infection (1); benign prostatic hyperplasia (1); benign tumors (1); bladder cancer (1); breast tumors (1); germ cell tumor (1); Infertility (1); metastatic prostate carcinoma (1); prostate tumor (1); seminoma (1); teratoma (1); tuberculosis (1).